ALDOA (aldolase, fructose-bisphosphate A)
Diseases named in the same sentence as ALDOA in open-access papers (continued):
Sharing a sentence is not in itself a finding about the gene and the disease.
tumor (continued). "Three genes (ZNF143, ALDOA and LEPROTL1) were among the top 30% of genes that are univariately informative of the proximity-to-tumour label." (PMID 29093438, 2017). "The activated networks (HIF1A, ESRRA, ESRRG) had many proteins that were increased in tumor tissues that overlapped between the three targets, such as ENO1/ENO2, ALDOA, and LDHA." (PMID 27128972, 2016). "Although to a lesser extent also HK2, ALDOA and ENO2 were identified as important players for tumor progression in vivo." (PMID 25932951, 2015). "Heterogeneous, but increased expression of ALDOA was found in RCC subtypes when compared to normal kidney cortex as well as in the serum of RCC patients and have been used for tumor staging." (PMID 25890500, 2015). "In the present study, we identified the glycolytic enzyme ALDOA was highly expressed in metastatic LSCC, and its express is highly correlated with LSCC metastasis, tumor grade and differentiation status." (PMID 24465716, 2014). "We further analyzed if there are any correlations between the protein level of ALDOA in LSSC tissues and tumor metastasis, grade and differentiation status." (PMID 24465716, 2014). "Additionally, the expression of glycolytic genes, including ALDOA and LDHA, was elevated in the cancer ductal population and colocalized with tumor markers." (PMID 41554705, 2026). "Transcriptome analysis indicated that the transcription level of ALDOA had no obvious change in sqr−/− tumor (1.21-fold)." (PMID 40305883, 2025). "However, a positive correlation was identified in molecules that promote tumor progression like VEGFA, ALDOA, and GPI." (PMID 40806276, 2025). "Consistently, the tumor volume of the HCCLM3-sgALDOA group was markedly smaller than the sgCtrl group, while xenograft tumors of ALDOA knockout group displayed similar intrahepatic dissemination and pulmonary metastases to the sgCtrl group on week 6 after transplantation." (PMID 40708574, 2025). "Additionally, ALDOA expression correlates with genomic instability markers, including MATH, ploidy, LOH, and HRD, suggesting its involvement in tumor heterogeneity and genomic instability across multiple cancers." (PMID 41239433, 2025). "Taken together, ALDOA and PKM may be critical targets for a novel anti-tumor approach in combination withTUG1 silencing to prevent HCC progression." (PMID 40696822, 2025). "AlDOA (Aldolase, Fructose-Bisphosphate A) catalyzes the conversion of fructose-1,6-bisphosphate to glyceraldehyde 3-phosphate (G3P) and dihydroxyacetone phosphate (DHAP) which is closely related to the Warburg Effect of tumor metabolism." (PMID 40486495, 2025). "LIPH (Lipase H), a membrane-associated phosphatidic acid-selective phospholipase A1a, is able to maintain the stability of ALDOA through activation of the LPA/LPAR axis, and directs ALDOA stability, directly connects PDAC cells to the tumor microenvironment, and promotes aberrant aerobic glycolysis." (PMID 40630951, 2025). "Additionally, ALDOA interacts with key oncogenic pathways, including the PI3K/AKT/mTOR and Wnt signaling cascades, further driving tumor aggressiveness." (PMID 41239433, 2025). "Genes involved in glycolysis (ALDOA, LDHA, PGK1, PFKL, PGM1) and other metabolic processes (GPX4, PRDX4, ACO2, ASPH, IDH2, SQLE, NPC2, SPTSSA) were upregulated in primary tumor cells, suggesting that the metabolism in primary tumors was distinct from that in their matched metastasis." (PMID 39225101, 2024). "In addition, we established a prediction model, and evaluated the predictive role of ALDOA expression on survival, as well as its correlation with AKT, a target related to tumor metabolism, to provide a novel strategy for CRC targeted therapy." (PMID 38499636, 2024). "More intuitively, the expression of ALDOA in majority tumor tissues was higher than that in paired normal tissues." (PMID 38499636, 2024).
tumor (continued). "While the extracellular tumor-linked roles of PGAM1, LDHA, PKM, TPI1, and PGK1 have not been tested, the anti-tumor actions of ALDOA 13, 18, ENO1 16, 18, and GAPDH 20 were reported." (PMID 37056934, 2023). "Together, these data establish a role for an essential metabolic protein, ALDOA in DNA DSB repair and suggests that targeting ALDOA may enable the concurrent targeting of cancer metabolism and DNA repair to induce tumour cell death." (PMID 37704669, 2023). "In vitro cell experiments have shown that interfering with DARS2 expression can inhibit the proliferation and migration of LUAD cells, promote cell apoptosis, and inhibit the glycolytic activity of tumor cells by inhibiting the expression of glycolytic related genes SLC2A1, GPI, ALDOA, and PGAM1." (PMID 37626419, 2023). "Interestingly, under hypoxic conditions, HIF-1α increases ALDOA expression, leading to increased lactate production and reducing the degradation of HIF-1α, subsequently promoting the invasive abilities of tumor cells." (PMID 35404841, 2022). "Indeed, the GPx2 KD tumor expressed notably higher levels of glucose transporter GLUT1 (SLC2A1), aldolase-A (ALDOA), phosphoglycerate kinase (PGK1), and lactate dehydrogenase A (LDHA) than in the control tumor." (PMID 35193955, 2022). "Of note, a negative correlation was observed from stage I to stage III, indicating that expression of ALDOA and FBP1 may play a role in tumor progression, especially during the early stages." (PMID 35404841, 2022). "Our results showed that ALDOA regulates the co-expression of TNFSF4 in a variety of tumors, which may have a certain correlation with the tumor’s immune microenvironment and prognosis." (PMID 35804089, 2022). "Targeting the ALDOA/FBP1 axis, it may be expected that the molecular regulation and reversal of glycolytic flux will reduce tumor malignancy." (PMID 35404841, 2022). "The results showed that tumor growth rate and tumor size were significantly inhibited after ALDOA knockdown compared to the negative control group." (PMID 33994862, 2021). "Through its impact on aerobic glycolysis, ALDOA can cause imbalance in the cancer microenvironment, and accumulating evidence has shown that ALDOA promotes proliferation and metastasis via its nonenzymatic functions in tumour cells." (PMID 34565365, 2021). "Knockdown of ALDOA significantly inhibited the proliferation and migration of ICC cells, while exogenously-induced overexpression of ALDOA enhanced the proliferation of tumor cells." (PMID 33994862, 2021). "However, the current expression of ALDOA in ICC is still unclear, and its regulatory mechanisms involved in tumor progression have yet to be studied." (PMID 33994862, 2021). "In conclusion, it can be seen that the proliferation, invasion and migration ability of tumor cells are improved to different degrees after ALDOA overexpression, but the level of improvement is not very significant." (PMID 33994862, 2021). "In our study, the proliferation and migration of tumor cells were significantly inhibited after inhibiting the catalytic activity of ALDOA enzyme by Itaconate without changing its expression level." (PMID 33994862, 2021). "Accordingly, over-expression of ALDOA and ALDOC were previously reported in various tumor types." (PMID 24993527, 2014). "Furthermore, immune checkpoint analysis revealed that ALDOA-high tumors exhibit reduced expression of key immune checkpoints, including PDCD1, CTLA4, and TIGIT, potentially reducing immune cell engagement with the tumor and further promoting immune evasion." (PMID 41239433, 2025). "However, the expression of the ALDOA protein did not correlate with other factors, such as age, gender, tumor location, degree of differentiation, tumor gross classification, microsatellite stabilization or the serum CA199 level (P > 0.05)." (PMID 39755705, 2025). "Therefore, ZNF692 may regulate ALDOA in HCC by modulating KAT5-mediated acetylation, thereby promoting glycolysis and tumor growth." (PMID 38453820, 2024).
tumor (continued). "Since ALDOA is a common metabolic enzyme, there is no research indicating whether it affects tumor progression in the form of enzymes." (PMID 33994862, 2021). "In line with this, the lactate levels increased both in tumor and peritumoral tissues, as well as the expression of glutamine transporters (i.e., SLC1A5) and glycolytic enzymes, such as glucose-6-phosphate isomerase (GPI), phosphoglycerate kinase (PGK1), aldolase A (ALDOA) and hexokinase 2 (HK2)." (PMID 33924061, 2021). "The tissue microarray immunohistochemical detection and analysis further verified the high expression of ALDOA in ICC tissues, and found that the increased expression of ALDOA was significantly correlated with the malignant degree of the tumor and the poor prognosis of the patients." (PMID 33994862, 2021). "Alternatively, tumor-derived ALDOA could be secreted (a non-canonical function described for some glycolytic enzymes) and act as a damage-associated molecular pattern (DAMP) or cytokine to directly engage receptors on macrophages, reinforcing their immunosuppressive polarization." (PMID 41239433, 2025). "Besides, our comparative analysis revealed that CRC tumor tissues with larger tumor size (P < 0.01), vascular invasion (P < 0.05), nerve invasion (P < 0.05) and positive serum CEA level (P < 0.001) showed higher ALDOA protein levels compared with their control counterparts, respectively." (PMID 39755705, 2025). "We found that stem cell-like GBM tumor subpopulations possessed higher basal levels of glycolytic activity and increased expression of several glycolysis-related enzymes including, GLUT1/SLC2A1, PFKP, ALDOA, GAPDH, ENO1, PKM2, and LDH, compared to their non-stem-like counterparts." (PMID 37420311, 2023).
cancer (111 papers, 2011 to 2026). A tumor composed of atypical neoplastic, often pleomorphic cells that invade other tissues. "Subsequent correlation analysis between ALDOA expression and macrophage markers further validated a significant association between ALDOA and macrophage infiltration in different cancer types." (PMID 41239433, 2025). "Cancer cells with ALDOA suppression exhibit increased susceptibility to ferroptosis-a response less obvious in normal cells." (PMID 41220277, 2025). "Owing to the process of gluconeogenesis and glycolysis ALDOA included in providing energy for the proliferation and migration in cancer cells, we investigated the association between ALDOA and the expression of AKT, a classical target of energy metabolism." (PMID 38499636, 2024). "Various pathways have been implicated in cancer tumorigenesis, cancer cell proliferation, migration and invasion, including regulation of the miR-329-3p/ALDOA axis, modulation of the miR-101/EZH2 axis, modulation of the miR-411-3p/HOXA10 pathway, and others." (PMID 38203269, 2023). "Little experimental evidence was reported about ALDOA ‘s association with immunocytes in cancers, but its potential roles in B cells, CD4+ T cells, and Th cells were noticed by GSEA." (PMID 36494582, 2023). "Considering the cancer malignancy-associated prognostic hypoxia factors, ALDOA is a therapeutic target, as it is induced by hypoxia in cancer cells and attention is increasing on glycolytic enzymes." (PMID 36077431, 2022). "In this study, we tried to investigate ALDOA-associated (AA) genes using available microarray datasets to help elucidating the role of ALDOA in cancer." (PMID 28191039, 2017). "Mechanistically, ALDOA has been implicated in metabolic reprogramming, facilitating the Warburg effect by enhancing glycolysis to meet the bioenergetic and biosynthetic demands of rapidly proliferating cancer cells." (PMID 41239433, 2025). "ALDOA, a glycolytic enzyme implicated in cancer, may link SDR42E1 to glucose metabolism and vitamin D regulation." (PMID 40756515, 2025). "Moreover, we found that depletion of ALDOA caused reduced cancer cell proliferation and extended survival in a mouse model of HCC." (PMID 39833612, 2025). "ALDOA (aldolase A), the most abundant isoform in cancer, is one of the key glycolytic enzymes that has been reported to be closely associated with patient prognosis and survival in cancer." (PMID 40696822, 2025). "In principle, this theranostic process could enable the therapeutic inhibition of ALDOA in cancer cells and its concomitant quantitative diagnostic detection by tracking the fluorescence response." (PMID 38792037, 2024). "However, the specific functions of ALDOA in cancer progression and the underlying mechanisms remain elusive." (PMID 37431681, 2023). "Recently, a new role of ALDOA in cancers has been proposed through its association with genes relevant to cell cycle independent of glycolysis and thus with the development and prognosis of several cancers." (PMID 35227895, 2022). "High expression of ALDOA is associated with the initiation and progression of many cancers." (PMID 36557005, 2022). "Since the most well-known and prevalent metabolic change associated with cancer cells is enhanced aerobic glycolysis, ALDOA is found to be highly expressed in many types of cancers acting as the oncogene, including renal clear cell, hepatocellular and lung squamous cell carcinomas." (PMID 34099027, 2021). "ALDOA could contribute to the progress of cancer, at least partially through its association with genes relevant to cell cycle independent of glycolysis." (PMID 28191039, 2017). "ALDOA might be a potential diagnostic and prognostic factor for cancer since ALDOA could distinguish tumors from controls and dramatically improve the predictive power of AA genes for poor survival." (PMID 28191039, 2017). "In rapidly proliferating cancer cells, the high expression of ALDOA better meets their substantial biosynthetic and energy demands." (PMID 41153403, 2025).
cancer (continued). "Recent studies have shown that ALDOA can hinder the polymerization of actin through the wiskott-aldrich syndrome protein pathway, thereby enhancing the motility of cancer cells." (PMID 40708574, 2025). "The mRNA expression levels of ALDOA are significantly higher various cancer types other than ESCA, PRAD and THYM, as assessed using data from TCGA." (PMID 41239433, 2025). "Consistent with the observations in vitro, the mRNA levels of c-Jun target genes, Cxcl1, Dusp1, Fgb, and Ppp1r15a, regulated by ALDOA were significantly decreased in the cancer tissues of AAV8-shAldoa mice compared with AAV8-GFP mice." (PMID 40708574, 2025). "In this study, we conducted a comprehensive pan-cancer analysis of ALDOA, with a particular focus on its expression patterns, prognostic significance, and genomic alterations in LUSC." (PMID 41239433, 2025). "In this view, Aldolase A (ALDOA), a key glycolytic enzyme, has been validated as a candidate oncogene in several cancers." (PMID 39755705, 2025). "The current investigation revealed a significant upregulation of ALDOA in numerous cancer types, accompanied by a notable suppression of cancer cell proliferation, migration, and invasion upon ALDOA knockdown." (PMID 40708574, 2025). "Instead, ALDOA seems to represent a unique metabolic dependency of cancer cells across multiple entities and conditions." (PMID 39833612, 2025). "To investigate the cell-type-specific expression of ALDOA across different cancer types, we performed single-cell RNA sequencing analysis using the TISCH2 database." (PMID 41239433, 2025). "Mechanistically, ALDOA depletion induces significant accumulation of fructose 1,6-bisphosphate in cancer cells, thereby enhancing autophagy-dependent degradation of phospholipid-modifying enzymes." (PMID 41220277, 2025). "Using the UCLAN database, we obtained the promoter methylation levels of ALDOA across various tumors, showing higher levels in some cancers and lower levels in others." (PMID 41239433, 2025). "We conducted a comprehensive pan-cancer analysis to evaluate ALDOA expression, genomic alterations, and prognostic relevance across different cancer types." (PMID 41239433, 2025). "Inhibition of ALDOA catalytic activity in highly glycolytic cancer cells thus leads to the induction of an imbalanced glycolytic state that effectively transforms glycolysis from an ATP-producing into an ATP-consuming pathway." (PMID 39833612, 2025). "In contrast, blocking glycolysis at the level of Gpi was fully tolerated by murine and human cancer cells, rendering them also insensitive to ALDOA depletion." (PMID 39833612, 2025). "ALDOA’s involvement in glycolytic pathways within the TME suggests its role in fueling cancer cell metabolism." (PMID 41584584, 2025). "Given its broad oncogenic functions, ALDOA has emerged as a potential prognostic biomarker and therapeutic target in multiple cancer types." (PMID 41239433, 2025). "Studies show that ALDOA is overexpressed in several cancers, including HCC, prostate cancer (PCa), and lung adenocarcinoma." (PMID 40076506, 2025). "ALDOA is often upregulated in cancers, particularly those aggressive phenotypes with high glycolytic activity and associated with poor prognosis." (PMID 41154605, 2025). "In this study, it is revealed that aldolase A (ALDOA) reprograms lipid metabolism to resist ferroptosis in cancer cells and identifies ALDOA as a targetable vulnerability for ferroptosis sensitization." (PMID 41220277, 2025). "Collectively, the findings reveal that ALDOA-mediated metabolic reprogramming is a targetable vulnerability for ferroptosis sensitization in cancer." (PMID 41220277, 2025). "ALDOA has also been shown to inhibit AMPK activation in cancer cells, possibly as a result of higher cellular ATP levels caused by enhanced glycolysis." (PMID 39755705, 2025). "Aldolase A (ALDOA) expression is upregulated in many cancer cells, and ALDOA increases intracellular lactate levels and induces H3K14 lactylation." (PMID 40333742, 2025).